HNRNPA2B1 (heterogeneous nuclear ribonucleoprotein A2/B1)
Diseases named in the same sentence as HNRNPA2B1 in open-access papers (continued):
Sharing a sentence is not in itself a finding about the gene and the disease.
melanoma (15 papers, 2017 to 2024). A malignant, usually aggressive tumor composed of atypical, neoplastic melanocytes. "To fully explore the role of YTHDF1 or HNRNPA2B1, we assessed their mutations using the cBioPortal Tool and found the two genes were mainly amplified in melanoma." (PMID 32549786, 2020). "We also observed major mutations in YTHDF1 and HNRNPA2B1 that led to their amplification in melanoma." (PMID 32549786, 2020). "Recent studies showed that HNRNPA2B1 with high frequency of mutation may have an influence on promoting tumorigenesis in melanoma." (PMID 33746977, 2021). "Finally, the study found that upregulating mutations in YTHDF1 and HNRNPA2B1 correlated with tumor stage and treatment response in patients, further supporting their roles, asm6A regulatory genes, in melanoma." (PMID 34105069, 2021). "One systematic analysis revealed that the expressions of YTHDF1 and HNRNPA2B1 were upregulated in melanoma." (PMID 34105069, 2021). "YTHDF1 and HNRNPA2B1 were significantly over-expressed in patients with melanoma while ELF3 was down-regulated." (PMID 32549786, 2020). "We further examined whether the combination of YTHDF1 and HNRNPA2B1 had higher efficacy in diagnosing melanoma by using linear regression and found the efficacy was improved from about 0.760 to 0.857 (P < 0.0001)." (PMID 32549786, 2020). "All the genes in the identified pathways were also positively related to YTHDF1 or HNRNPA2B1, suggesting the expression of both genes might influence m6A modifications in mRNA genes and potentially result in melanoma heterogeneity at the cellular level." (PMID 32549786, 2020). "The results revealed the up-regulation of YTHDF1 and HNRNPA2B1 in melanoma." (PMID 32549786, 2020). "Statistical analysis revealed the significance of YTHDF1 and HNRNPA2B1 and the combination of the two genes may provide a better approach to diagnose melanoma." (PMID 32549786, 2020). "Several m6A regulators including METTL3, YTHDF1, HNRNPA2B1, FTO, and IGF2BP3 are involved in melanoma." (PMID 37124930, 2023). "Comparing primary melanoma and metastases, we found that ALKBH5, ELAVL1, FMR1, HNRNPA2B1, HNRNPC, IGF2BP1/2/3, KIAA1429, LRPPRC, RBM15, YTHDC1/2, YTHDF1/3, and ZC3H13 were significantly upregulated in metastases, while RBM15B and METTL3 were significantly upregulated in primary melanoma." (PMID 34993195, 2021). "Moreover, YTHDF1 or HNRNPA2B1 might interact with RNA processing-related genes such as CDK1/CDK2 and further promote the formation and progression of melanoma." (PMID 32549786, 2020).
colon carcinoma (14 papers, 2020 to 2025). "First, by analyzing Oncomine and TCGA databases, we found that hnRNPA2B1 is highly expressed in colon cancer and is associated with poor disease-free interval and poor prognosis." (PMID 34630502, 2021). "In this study, we aimed to elucidate the biological functions of hnRNPA2B1 and to explore its underlying mechanisms in colon cancer." (PMID 34630502, 2021). "Similarly, in colon cancer, a prognosis-associated gene HNRNPA2B1 was reported to affect cancer cells through the MAPK signaling pathway." (PMID 37925483, 2023). "hnRNPA2B1 is abundantly expressed in colon cancer and significantly expedites colon cancer growth in vitro and in vivo." (PMID 39810713, 2025). "GO analyses have shown that hnRNPA2B1 significantly influences alternative splicing events in colon cancer cells that overexpress hnRNPA2B1, suggesting a crucial role in colon cancer progression." (PMID 37850412, 2023). "Studies have shown that hnRNPA2B1 promotes colon cancer cell proliferation, and the knockout of hnRNPA2B1 significantly induces apoptosis and cell cycle arrest." (PMID 37152066, 2023). "Data from analyses of western blot indicated that hnRNPA2B1 expression level was significantly upregulated in human colon carcinoma compared with normal colon tissues." (PMID 34630502, 2021). "Proliferation of hnRNPA2B1 knockout cells was significantly lower than the control group, indicating that the knockout of hnRNPA2B1 can impair the proliferation ability of colon cancer cells in vitro." (PMID 34630502, 2021). "Further investigation needs to be conducted to confirm the oncogenic role of hnRNPA2B1 in colon cancer, so subcutaneous tumor formation experiments were performed in nude mice." (PMID 34630502, 2021). "Currently, it is difficult to confirm what kinds of detailed mRNA modifications mediated by hnRNPA2B1 participate in colon cancer development and progress." (PMID 34630502, 2021). "Collectively, these experiments indicated that knockout of hnRNPA2B1 in colon cancer cells decreases cell proliferation and increases apoptosis in vitro." (PMID 34630502, 2021). "To investigate possible molecular mechanisms of hnRNPA2B1 involved in colon cancer pathogenesis and progression, we performed the RNA-seq analyses." (PMID 34630502, 2021). "We used CRISPR/Cas9 directed gene editing to knockout hnRNPA2B1 expression in human colon cancer cell line SW480 and HCT-116 and carried out both in vivo and in vitro experiments." (PMID 34630502, 2021). "Western blot analyses confirmed that hnRNPA2B1 expression was essentially abolished in colon cancer cell line in which hnRNPA2B1 was knockout all." (PMID 34630502, 2021). "As hnRNPA2B1 is one of m6A-related genes, we then turned our attention to expression of all 21 m6A-related genes in colon cancer." (PMID 34630502, 2021). "We found that hnRNPA2B1 significantly promoted colon cancer cell proliferation both in vitro and in vivo, while knockout of hnRNPA2B1 induced apoptosis and cell cycle arrest in SW480." (PMID 34630502, 2021). "To validate the selective high expression levels of hnRNPA2B1, we performed Western blot or RT-qPCR analyses in 4 colon cancer cell lines including SW620, SW480, HCT-8, HCT-116 and normal intestinal epithelial cells NCM460 as well as clinical colon samples." (PMID 34630502, 2021). "hnRNPA2B1 is a potential diagnosis and therapeutic target for colon cancer, considering its role in post-transcriptional modification m6A modification and alternative splicing." (PMID 34630502, 2021). "The results showed that tumors generated by hnRNPA2B1 knockout cells were significantly smaller than control, indicating that hnRNPA2B1 facilitated colon cancer tumorigenesis in vivo." (PMID 34630502, 2021). "To determine possible functions of hnRNPA2B1 in colon cancer, we used CRISPR/Cas9 directed gene editing to knockout hnRNPA2B1 expression in human colon cancer cell lines SW480 and HCT-116." (PMID 34630502, 2021).
colon carcinoma (continued). "Still other studies have found that HNRNPA2B1 can promote cell proliferation and regulate apoptosis of human colon cancer via the ERK/MAPK signaling, which indicates HNRNPA2B1 provides a potential treatment site for colon cancer." (PMID 34899855, 2021). "In this study, we demonstrate that hnRNPA2B1 promotes the progression of colon cancer by regulating the ERK/MAPK signaling pathway." (PMID 34630502, 2021). "Secondly, by western blotting and immunohistochemistry, upregulation of hnRNPA2B1 expression is confirmed in colon cancer cells and clinical samples." (PMID 34630502, 2021). "Taken together, these results support the model that hnRNPA2B1 positively regulates the activation of the ERK pathways to promote cell proliferation in colon cancer." (PMID 34630502, 2021). "Several RBPs have been previously identified as mediators of exosome miRNA sorting in various model systems, including major vault protein in colon cancer cells, hnRNPA2B1 in T cells, and YBX1 in HEK293T cells." (PMID 32819370, 2020). "As C. orbiculata reduced the B1 isoform of hnRNPA2B1, we mimicked this by siRNA knockdown specifically of the hnRNPB1 isoform in HCT116 colon cancer cells." (PMID 33163396, 2020). "We evaluated the association of hnRNPA2B1 with BCL2L1, BCL2, MDM2, cMYC, CD44, CDK6, cJUN, and TXNP in HCT116 colon cancer cells treated with 70 μg/ml of the crude extract." (PMID 33163396, 2020). "Treatment of HCT116 colon cancer cells with 70 μg/ml of C. orbiculata extract resulted in an increase in the co-precipitation of hnRNPA2B1 with BCL2L1, BCL2, MDM2, cMYC, CD44, CDK6, and cJUN mRNA." (PMID 33163396, 2020). "There is a question of does hnRNPA2B1 affects the immune status of colon cancer progression?" (PMID 34630502, 2021). "Our sequencing results also show that hnRNPA2B1 is highly expressed the frequency of alternative splicing events in colon cancer is increased under the circumstances, which indicates alternative splicing may play an important role in colon cancer." (PMID 34630502, 2021). "Meanwhile, the CCK8 assay also confirmed that the proliferation of HCT-8 increased after the hnRNPA2B1 overexpression, and the effects of hnRNPA2B1 were blocked after inhibiting the MAPK signaling, which further supported that hnRNPA2B1 promotes colon cancer progression via the MAPK pathway." (PMID 34630502, 2021). "In addition, we examined and compared the expression of hnRNPA2B1 in 8 pairs of colon cancer tissues and normal colon tissues." (PMID 34630502, 2021). "Interestingly, we have also observed the effect of hnRNPA2B1 on alternative splicing in colon cancer from TCGA." (PMID 34630502, 2021). "Similarly, higher expression levels of hnRNPA2B1 were also observed in tumor tissues (Ki67 positive) of colon cancer patients by IHC assay." (PMID 34630502, 2021). "hnRNPA2B1 has been proposed as a therapeutic target for anticancer therapy, but there are no previous reports of naturally occurring agents that can switch on targeting splicing to switch off B1 in colon cancer." (PMID 33163396, 2020). "Targeting hnRNPA2B1 splicing in colon cancer regulates splicing of BCL2L1 to induce apoptosis." (PMID 33163396, 2020). "Thus, hnRNPA2B1 was upregulated in established colon cancer lines and colon cancer tissues." (PMID 34630502, 2021). "Compared to normal colon tissues, a great number of m6A regulators with CNV deletions had lower expression in colon cancer tissues (for instance, ALKBH5), and vice versa (e.g., YTHDF1, IGF2BP2, HNRNPA2B1, etc.)." (PMID 36119534, 2022). "IHC staining results show that hnRNPA2B1 and p-ERK are partially co-expressed in colon cancer tissue due to tumor heterogeneity, which indicates that there is a regulatory basis between them." (PMID 34630502, 2021). "The effects of C. orbiculata was similar to those of pladienolide B in that, just like C. orbiculata, pladienolide B switches splicing of hnRNPA2B1 and BCL2L1 to induce apoptosis in HCT116 colon cancer cells." (PMID 33163396, 2020).
colon carcinoma (continued). "Moreover, IHC staining results show that hnRNPA2B1 and p-ERK are partially co-expressed in colon cancer tissue due to tumor heterogeneity, which indicates that there is a regulatory basis between them." (PMID 34630502, 2021). "In conclusion, the present work is the first to show the expression, function and putative mechanism of hnRNPA2B1 with respect to cell proliferation and apoptosis in the setting of colon cancer and to propose that the ERK/MAPK pathway is activated by hnRNPA2B1 during this development process." (PMID 34630502, 2021). "On one hand, hnRNPA2B1 appears to be an important regulator of ERK/MAPK pathway, but whether or not it directly or indirectly activities the MAPK pathway gene in colon cancer remains to be determined." (PMID 34630502, 2021). "It demonstrates that hnRNPA2B1-ERK/MAPK signal axis, which promotes colon cancer progression." (PMID 34630502, 2021). "In addition, both hnRNPA2B1 and MAPK pathway were activated in clinical colon cancer specimens and positively correlated." (PMID 34630502, 2021).
prostate carcinoma (14 papers, 2014 to 2024). A carcinoma that arises from epithelial cells of the prostate gland. "In conclusion, our present study showed that HNRNPA2B1 expression was highly increased in prostate cancer and associated with poor prognosis of prostate cancer patients." (PMID 37215455, 2023). "The present study revealed that HNRNPA2B1 was significantly elevated in prostate cancer and the high level of HNRNPA2B1 was strongly associated with poor prognosis." (PMID 37215455, 2023). "HNRNPA2B1 is highly expressed in many cancers, such as pancreatic, breast and prostate cancers, and malignant gliomas, where HNRNPA2B1 plays an important role in carcinogenesis, invasion and metastasis." (PMID 37671941, 2023). "Here, we found that HNRNPA2B1 was highly overexpressed and correlated with a poor prognosis in prostate cancer." (PMID 37215455, 2023). "In vitro and in vivo functional experiments demonstrated that HNRNPA2B1 knockout impaired proliferation and metastasis of prostate cancer." (PMID 37215455, 2023). "To identify the major target genes of HNRNPA2B1/miR-93-5p in prostate cancer, we performed an integrative analysis of StarBase, TargetScan, and miRDIP database and obtained seven candidate target genes." (PMID 37215455, 2023). "The significant upregulation of HNRNPA2B1 in prostate cancer and strong correlation between HNRNPA2B1 and poor clinicopathological characteristics prompted us to further explore its role in tumor proliferation and invasion of PCa." (PMID 37215455, 2023). "We found that HNRNPA2B1 was highly expressed in prostate cancer and related to adverse clinicopathological features and poor prognosis." (PMID 37215455, 2023). "We next performed qRT-PCR analysis to quantify the levels of these six mature miRNAs and found that only miR-17-5p, miR-93-5p, and miR-425-5p were decreased in HNRNPA2B1 knockout prostate cancer cells." (PMID 37215455, 2023). "In vivo subcutaneous xenograft tumor model revealed that HNRNPA2B1 depletion significanly suppress tumorigenic ability of prostate cancer." (PMID 37215455, 2023). "These particular results indicated that HNRNPA2B1 accelerated the maturation of miR-93-5p in an m6A-dependent manner in prostate cancer." (PMID 37215455, 2023). "Subsequently, we determined CBLL1, FTO, YTHDC1, HNRNPA2B1 as crucial m6A regulators of prostate cancer." (PMID 34899855, 2021). "In summary, the current data demonstrate that Enza-induced increase of PCAT6 expression promotes prostate cancer neuroendocrine differentiation by regulating miR-326/Hnrnpa2b1 axis." (PMID 34277403, 2021). "It was found that the expression of METTL14, IGF2BP3, HNRNPA2B1, and CNV of ALKBH5 were linked to the recurrence-free survival of prostate cancer." (PMID 34899855, 2021). "Relevance to clinical features and independent contribution to both overall and disease-free survival highlighted the importance of the translation initiation factor subunit EIF3D and the splicing factor HNRNPA2B1 in prostate cancer." (PMID 33273988, 2020). "Given the prognostic importance of EIF3D and HNRNPA2B1 for both overall and disease-free survival, we investigated their roles in prostate cancer." (PMID 33273988, 2020). "A total of 1346 genes showed dependence of alternative splicing on both HNRNPA2B1 and m6A in prostate cancer (Supplementary Excel S8)." (PMID 33273988, 2020). "High expression of HNRNPA2B1 progressed the proliferation of prostate cancer in elevating endogenous beta-catenin mRNA translation and nuclear localization." (PMID 32710725, 2020). "To investigate which set of miRNAs were regulated by HNRNPA2B1 in prostate cancer, we combined the HNRNPA2B1-modulated miRNA data from a previous study 12 and TCGA data of upregulated miRNAs in prostate cancer, and obtained six potential downstream miRNAs that intersected on the Venn diagram." (PMID 37215455, 2023). "In the present study, we focused on the m6A-related function of HNRNPA2B1 in prostate cancer." (PMID 37215455, 2023).